RNASE3 (ribonuclease A family member 3)
Description:
Cytotoxin and helminthotoxin with low-efficiency ribonuclease activity. Possesses a wide variety of biological activities. Exhibits antibacterial activity, including cytoplasmic membrane depolarization of preferentially Gram-negative, but also Gram-positive strains. Promotes E.coli outer membrane detachment, alteration of the overall cell shape and partial loss of cell content.
Synonyms: ECP; RNS3; RAF1
Tractability: Small molecule: a structure with a bound ligand is known; it has a binding pocket of medium quality. Antibody: its Gene Ontology location is reachable by antibodies, with high confidence; UniProt places it where antibodies can reach, with medium confidence; UniProt predicts a signal peptide or a membrane-spanning region. PROTAC: its protein half-life has been measured.
Gene: Protein-coding gene on chromosome 14 (20,891,385 to 20,892,348, forward strand). Ensembl gene ENSG00000169397.
Subcellular location: Secreted
Pathways (Reactome):
Immune System: Antimicrobial peptides; Neutrophil degranulation
Gene Ontology:
Molecular function: lipopolysaccharide binding; RNA nuclease activity; nucleic acid binding
Biological process: antibacterial humoral response; antimicrobial humoral immune response mediated by antimicrobial peptide; defense response to Gram-negative bacterium; defense response to Gram-positive bacterium; induction of bacterial agglutination; innate immune response; innate immune response in mucosa; chemotaxis; RNA catabolic process
Cellular component: extracellular region; azurophil granule lumen
Genetic constraint (gnomAD): Loss-of-function variants: 1 observed, 0.25 expected, observed/expected ratio (o/e) 3.94. That is too few expected variants to judge how well the gene tolerates losing a copy. Missense variants: 192 observed, 215.03 expected, observed/expected ratio (o/e) 0.89, 90% interval 0.79 to 1.01. Synonymous variants: 66 observed, 76.42 expected, observed/expected ratio (o/e) 0.86, 90% interval 0.71 to 1.06.
Homologues: Orthologues: macaque RNASE3 (89% identical), mouse Ear1 (48% identical), rat Ear1l1 (48% identical), rat Rnase17 (48% identical), mouse Ear10 (48% identical), mouse Ear2 (47% identical), mouse Rnase2a (47% identical), rabbit RAF2 (47% identical), mouse Ear6 (46% identical), rat Ear1 (46% identical), rat Rnase2 (46% identical), mouse Rnase2b (44% identical), and 1 more. Paralogues in human: RNASE2 (69% identical), RNASE6 (41% identical), RNASE7 (39% identical), RNASE8 (38% identical), RNASE1 (28% identical), RNASE4 (25% identical), ANG (22% identical), RNASE10 (20% identical), RNASE9 (20% identical), RNASE13 (16% identical), RNASE11 (13% identical), RNASE12 (12% identical).
Diseases named in the same sentence as RNASE3 in open-access papers:
RNASE3 is named in the same sentence as 144 diseases in open-access papers, as found by Europe PMC text mining. Sharing a sentence is not in itself a finding about the gene and the disease. The quoted sentences say what the papers report.
asthma (123 papers, 2006 to 2026). "In accordance, we found the eosinophil marker genes RNASE2 (ribonuclease A family member 2), RNASE3, SIGLEC8 (sialic acid binding Ig-like lectin 8) and IL5RA as well as PRSS33 (serine protease 33) being exclusively expressed in eosinophils in the deconvolved asthma data." (PMID 33076907, 2020).
allergic asthma (14 papers, 2008 to 2025). A asthma with a basis in a pathological type I hypersensitivity reaction. "Others studies showed a genetic relationship between RNASE3 SNPs with the expression of diseases such as allergic asthma, parasite infectious and/or inflammatory diseases." (PMID 29402293, 2018).
malaria (6 papers, 2011 to 2022). Malaria is a serious and sometimes fatal disease caused by a parasite that commonly infects a certain type of mosquito which feeds on humans. "In this work, RNASE3 gene polymorphisms was analysed in malaria patients from Senegal (West Africa)." (PMID 29402293, 2018). "The present study aims to investigate RNASE3 gene polymorphisms and their putative link to severe malaria in a malaria cohort from Senegal." (PMID 29402293, 2018). "In the present study, we have sequenced RNASE3 and investigated the association between SNPs and susceptibility to CM in a hospital based malaria study involving CM, SA and UM patients." (PMID 22216286, 2011). "Analyses were conducted to test whether RNASE3 +499G/C genotypes were associated with malaria severity." (PMID 29402293, 2018). "Presence of an R at 97 position has been linked to an enhanced severity of malaria and schistosomiasis side-effects, such as hepatic fibrosis or neurological disorders, that might be associated to an overabundance of the secreted RNase3 at the infectious focus." (PMID 33226440, 2021). "RNASE3 gene and its flanking regions were sequenced in samples from a cohort of urban individuals including healthy controls, uncomplicated malaria (UM) and SM subjects." (PMID 29402293, 2018). "The genetic association identified independently in the Senegalese population provide additional evidence of a role of RNASE3 (ECP) in malaria severity." (PMID 29402293, 2018). "In this study, an analysis of the RNASE3 (ECP) gene were performed, in order to identify polymorphisms associated with severe malaria in the Senegalese population." (PMID 29402293, 2018). "The RNASE3 gene and flanking regions were amplified from 206 Ghanaian children enrolled in a hospital based malaria study." (PMID 22216286, 2011). "The RNASE3 gene and flanking regions were sequenced in 206 Ghanaian children enrolled in a hospital based malaria study." (PMID 22216286, 2011). "One of our recent studies showed that Ribonuclease 3 (RNASE 3), also known as eosinophil cationic protein (ECP), is one of the factors suggested as having a role in malaria severity." (PMID 35811813, 2022). "Ribonuclease 3 (RNASE 3), also known as eosinophil cationic protein (ECP), is one of the factors suggested as having a role in malaria severity." (PMID 29402293, 2018).
cerebral malaria (5 papers, 2011 to 2021). A sequestration of Plasmodium falciparum in the brain, which can cause coma and/or seizures. "RNASE3 (ECP) has been identified as an inhibitor of Plasmodium parasites growth in vitro, and genetic analysis in hospitalized Ghanaian subjects has revealed the RNASE3 +371G/C (rs2073342) polymorphism as a susceptibility factor for cerebral malaria." (PMID 29402293, 2018).
viral infection (5 papers, 2014 to 2025). "The observed gene expression pattern induced by RNase3 is characteristic of both EGFR- and IFN-associated pathways, which can participate in the macrophage response to bacterial and viral infection, respectively." (PMID 33226440, 2021). "The results revealed that RNase3 can inhibit both bacterial and viral infection through the modulation of the macrophage immune response in both ribonucleolytic-dependent and independent ways." (PMID 33226440, 2021). "However, the potential application of RNase3 in controlling sweet potato viral diseases remains underexplored." (PMID 40699641, 2025). "Further exploration of RNase3 could provide valuable insights for managing SPVD and other viral diseases in sweet potatoes." (PMID 40699641, 2025).
co-infection (3 papers, 2013 to 2023). "The important function known for SPCSV RNase3 is its ability to eliminate antiviral defence, which also predisposes sweetpotato plants to development of severe disease symptoms following co-infection with heterologous viruses." (PMID 24278443, 2013).
acute myeloid leukemia (1 paper, 2021). Acute myeloid leukemia (AML) is a group of neoplasms arising from precursor cells committed to the myeloid cell-line differentiation. "In addition to upgraded expression levels of acute myeloid leukemia-related genes during leukemic transformation, expression levels of some inflammation-related genes (such as S100s, RNASE3, and CYBB) were also increased, and inflammation-related pathways were up-regulated." (PMID 34229751, 2021).
HIV-1 infection (1 paper, 2017). The type species of lentivirus and the etiologic agent of acquired immunodeficiency syndrome (AIDS). "The authors linked the downregulation of RNASE2, RNASE3 and RNASE6 to enhanced susceptibility of Th17 cells HIV-1 infection." (PMID 28241075, 2017).
macrosomia (1 paper, 2023). "The 9 indicators verified by nomogram in this analysis, including pre-pregnancy BMI, weight gain at 24 gw, parity, OGTT 2 h glucose at 24 gw, HDL and LDL at 24 gw, and plasma expression of CLUL1, VCAN and RNASE3 at 24 gw, are very meaningful in terms of identifying macrosomia risk in GDM." (PMID 36788507, 2023). "The roles of FCRL1 and RNASE3 in inflammatory pathways point to an important role of the immune system in metabolic pathology in GDM related macrosomia." (PMID 36788507, 2023). "The Model included pre-pregnancy BMI, weight gain at 24 gw, parity, OGTT 2 h glucose at 24 gw, HDL and LDL at 24 gw, and plasma expression of CLUL1, VCAN and RNASE3 at 24 gw had good prediction performance for predicting macrosomia in women with GDM." (PMID 36788507, 2023).
nematode infections (1 paper, 2023). "It is well documented that activated eosinophils release granule proteins, such as Ribonuclease (RNAS2 and RNASE3), eosinophil cationic protein (ECP), MBP, and EPO following nematode infections." (PMID 37283884, 2023).
oral cancer (1 paper, 2021). "In our study, the increased ECP suggested a poor prognosis of OCSCC, which was in line with the qRT-PCR results that showed higher expression of ECP (RNASE3) in oral cancer cell line." (PMID 34585646, 2021).
osteosarcoma (1 paper, 2019). A usually aggressive malignant bone-forming mesenchymal neoplasm, predominantly affecting adolescents and young adults. "A combination of eight genes (RAB1,CLEC3B,FCGBP,RNASE3,MDL1,ALOX5AP,VMO1 and ALPK3) were identified as being associated with osteosarcoma metastasis." (PMID 30868060, 2019).
Sepsis (1 paper, 2024). Sepsis is defined as life-threatening organ dysfunction caused by a dysregulated host response to infection. "Meta-random-effects model analysis showed that elevated expression levels of ELANE, FCGR1A, IL1R2, and RNASE3 were associated with sepsis." (PMID 39655195, 2024). "In the sepsis group, FCGR1A and TLR5 were positively associated with survival compared to ELANE, IL1R2, RAB13, and RNASE3, which were adversely associated with survival." (PMID 39655195, 2024). "Six core genes, ELANE, IL1R2, RAB13, RNASE3, FCGR1A, and TLR5, have been linked to sepsis prognosis." (PMID 39655195, 2024). "Importantly, our findings indicate that high expression levels of ELANE, IL1R2, RAB13, and RNASE3 promote death rates in sepsis, whereas high expression levels of FCGR1A and TLR5 improve the survival rate of patients with sepsis." (PMID 39655195, 2024). "ELANE, IL1R2, RAB13, and RNASE3 promote cell death, whereas FCGR1A and TLR5 facilitate cell survival in sepsis." (PMID 39655195, 2024). "Analysis of clinical prognostic data (dataset: GSE65682) in the context of sepsis revealed that the upregulation of ELANE, IL1R2, RAB13, and RNASE3 affected prognosis by reducing the survival rate of patients with sepsis." (PMID 39655195, 2024). "In summary, these findings suggest that ELANE, IL1R2, RAB13, RNASE3, FCGR1A, and TLR5 may influence the prognosis of patients with sepsis and provide novel insights and potential avenues for the treatment of sepsis." (PMID 39655195, 2024).
tumor (24 papers, 2009 to 2026). "The expression levels of CLDN18 (P = 4.4e-04) were significantly higher in HCC tissues compared to the normal tissues, whereas METTL7B, ITGA9, SOCS3 and RNASE3 were downregulated in the tumor tissues." (PMID 37438735, 2023). "Analysis of the TNMplot database indicated similar expression of METTL7B and RNASE3, downregulation of ITGA9 and SOCS3, and upregulation of CLDN18 in the tumor tissues relative to the adjacent normal tissues." (PMID 37438735, 2023). "Using an eosinophil gene signature (SIGLEC8, RNASE2, RNASE3, IL5RA, and CCR3), it was found that eosinophil infiltration inside the tumor correlates with increased CD8+ T cell and IFN-γ signatures and was shown that tumor eosinophils enhance CD8+ T cell activation, leading to tumor eradication." (PMID 39496729, 2024). "Among them CCNB1, MIF, PLA2G4A may be regarded as oncogenes, whereas RNASE3, APOE, FOXO1, KIT, and EGR1 may be tumor suppressor genes." (PMID 37065484, 2023).
infection (21 papers, 2011 to 2024). The state of being infected such as from the introduction of a foreign agent such as serum, vaccine, antigenic substance or organism. "RNASE3 has been associated with schistosomiasis infection, infection intensity and fibrosis in a study that was conducted among the Alur speaking community of Lake Albert." (PMID 38033168, 2023). "Five genes have been associated with both fibrosis and intensity of infection (RNASE3, IL4, IL10, IFNGI, and IL13)." (PMID 33659002, 2021). "RNase3 is sufficient to render sweetpotato (Ipomoea batatas) virus-susceptible and predisposes it to development of severe diseases following infection with unrelated virus." (PMID 24278443, 2013). "The two prominent RNases, EDN (RNase 2) and ECP (RNase 3), are found in saliva, with increased expression during illness and infection." (PMID 35626342, 2022). "The RNase3 overexpression macrophages were treated with Erlotinib for 24 h before infection of either M. aurum or RSV." (PMID 33226440, 2021). "Next, we demonstrated that overexpression of macrophage endogenous RNase3 protects the cells against infection by Mycobacterium aurum and the human respiratory syncytial virus." (PMID 33226440, 2021). "A significant growth inhibition of M. aurum in RNase3 overexpression macrophages was detected at 24 h post-infection compared to WT macrophage." (PMID 33226440, 2021). "We conclude that RNase3 modulates the macrophage defence against infection in both catalytic-dependent and independent manners." (PMID 33226440, 2021). "The present time-course expression profiles in M. aurum infected THP1 macrophages indicates a downregulation of RNase3 and RNase6 after a short infection period followed by a significant upregulation at longer incubation times." (PMID 31312205, 2019). "Rnase3 is an antimicrobial protein secreted in response to infection, and is critical for neutralizing bacterial lipopolysaccharides (LPS) and inhibiting tumor necrosis factor production in human macrophages." (PMID 29443944, 2018). "The eosinophil ribonucleases, EDN (eosinophil derived neurotoxin, RNase2) and ECP (eosinophil cationic protein, RNase3), are two secretory ribonucleases stored in the secondary granules of eosinophils and released at the focus of infection." (PMID 27089320, 2016). "Individuals with polymorphisms in loci containing IL6, IL10, FCN2, RNASE3 and multiple Th17 pathway genes such as IL12B and IL17B had varying worm burden, indicating that these loci may play a role in determining infection intensity." (PMID 38033168, 2023). "Unfortunately, RNase3 pro-inflammatory action following infection might also have a detrimental effect on the host tissues." (PMID 33226440, 2021). "In particular, RNase3 is abundantly secreted by eosinophils during inflammation and infection." (PMID 33226440, 2021). "Next, we evaluated the efficacy of the macrophage endogenous RNase3 against infection." (PMID 33226440, 2021). "It is alone sufficient to eliminate antiviral defence to unrelated viruses in RNase3-transgenic sweetpotato plants and predisposes sweetpotato to development of the severe sweetpotato virus disease (SPVD) following infection with Sweet potato feathery mottle virus (SPFMV; Potyvirus, Potyviridae)." (PMID 24278443, 2013). "In addition, RNase3 expression is induced by infection and might contribute to the protection of biological fluids." (PMID 33226440, 2021). "RNase3, also known as the eosinophil cationic protein (ECP), is mainly expressed during infection and inflammation in the secondary granules of eosinophils and secondarily in neutrophils." (PMID 29163551, 2017). "On its turn, RNase 3, another of the main antimicrobial RNases within the RNase A superfamily, also called the Eosinophil Cationic Protein (ECP), is involved in inflammatory processes mediated by eosinophils and is released by the secondary granules upon infection." (PMID 27277554, 2016).
infection (continued). "In addition, we explored whether the cell infection by M. aurum and RSV could regulate the macrophage endogenous RNase3 expression." (PMID 33226440, 2021). "Complementarily, we built an RNase3 overexpression THP1 cell line by CRISPRa to validate the transcriptome results and evaluated the direct contribution of the endogenous protein in the eradication of intracellular infection by M. aurum and the human respiratory syncytial virus (RSV)." (PMID 33226440, 2021).
cardiovascular disease (3 papers, 2022 to 2025). "An important result of proteomics approach was the identification of RNase2 and RNase3 only in neutrophils from some of the obese patients with cardiovascular disease." (PMID 35818731, 2022).
bacterial infection (2 papers, 2018 to 2021). "Our results are not only useful for the research of Rnase2 and Rnase3 evolution, but also help further elucidation of the regulation mechanisms in the innate immune response of M. amblycephala to bacterial infection." (PMID 29443944, 2018). "In following studies, we will focus on the protein expression and biological function of Ma-Rnase2 and Ma-Rnase3; especially on the antibacterial mechanism of Rnase3 and experimental studies of bacterial infection both in vitro and in vivo." (PMID 29443944, 2018).
RNASE3 also shares sentences with these, for which no sentence is quoted: eosinophilia (41 papers); allergic disease (32); allergic rhinitis (21); Allergy (17); nasal polyps (17); rhinitis (12); inflammation (10); atopic dermatitis (9); parasitic infections (7); polyp (7); melanoma (5); metastatic melanoma (5); airway hyperresponsiveness (4); atherosclerosis (4); bronchiolitis (4); helminth infections (4); schistosomiasis (4); childhood asthma (3); chronic rhinosinusitis (3); colitis (3); coronary artery disease (3); cystic fibrosis (3); eosinophilic diseases (3); gastroesophageal reflux disease (3); lung disease (3); metastatic disease (3); Obesity (3); RSV bronchiolitis (3); Airway obstruction (2); cancer (2).
A further 97 diseases each share a sentence with RNASE3 in 2 papers or fewer.